CCND1 (cyclin D1)
Diseases named in the same sentence as CCND1 in open-access papers (continued):
Sharing a sentence is not in itself a finding about the gene and the disease.
glioma (241 papers, 2008 to 2026). A benign or malignant brain and spinal cord tumor that arises from glial cells (astrocytes, oligodendrocytes, ependymal cells). "Cyclin D1 expression has been shown to be associated with the pathological grade and aggressiveness of glioma, the prognosis of patients with glioma, and the response to chemotherapy." (PMID 36045715, 2022). "As a well-known oncogene, TCGA data showed that high expression of c-Myc was also found to be associated with poor prognosis of glioma patients with an AUC of 0.992, which was also positively correlated with CCND1 expression." (PMID 35365622, 2022). "Our data showed that silencing BYSL caused cell cycle arrest at G1 phase in glioma cells, which was further verified by the downregulation of cyclin D1 and CDKs (CDK4 and CDK6) and the upregulation of CDKIs (P21 and P27)." (PMID 33628587, 2021). "Apoptosis: MALAT1 knockdown increased apoptosis and expression of apoptotic regulators, including MYC and CCND1 (encoding cyclin D1) in glioma." (PMID 34322395, 2021). "The top three genes found in the Glioma signaling network, CCND1, CDKN2A, and RB1, are frequently overexpressed, mutated, and/or deleted in glioma]." (PMID 29912931, 2018). "Significantly, AMPKα mutation or knockdown restored mTOR activation and cyclin D1 expression in glioma cells." (PMID 27532105, 2016). "To investigate the association between miR-15b and Cyclin D1 expression in glioma, we analyzed Cyclin D1 expression by real-time PCR." (PMID 24995320, 2014). "In addition, numerous studies have reported that CCND1/RAP1B is associated with glioma cell proliferation and invasion." (PMID 33676540, 2021). "Our findings suggested that CCND1 rs603965 polymorphism may serve as a potential genetic biomarker of brain tumor, especially for glioma." (PMID 30972946, 2019). "In summary, our meta‐analysis suggested that the CCND1 rs603965 polymorphism may serve as a potential genetic biomarker of brain tumor, especially for glioma." (PMID 30972946, 2019). "To examine whether Smad6 contributes to STAT3 activation, we first analyzed proteins downstream of STAT3 associated with glioma stemness, including c-jun, CCND1, and Sox2." (PMID 29950561, 2018). "The results of this study suggest that CCND1 G870A genetic variants may modify the influence of EFEMP1- rs1346787 gene on glioma risk." (PMID 28380465, 2017). "Not surprisingly, siRNA targeting of β-catenin, which is elevated in immunohistochemical analysis of glioma specimens, also arrested cells in G1 and caused decreased activation of c-Myc, c-jun and cyclin D1, while also inducing apoptotic cell death in glioma cells." (PMID 27043632, 2016). "This hypothesis is supported by the observations: MAGI3 overexpression downregulated the expression of c-Myc and Cyclin D1, which are target genes of β-catenin and appear to be associated with glioma progression." (PMID 26452219, 2015). "Downregulation of CCND1 leads to accumulation of a subset of glioma cells at G0/G1 which might be the underlying mechanism of low proliferative capabilities of glioma cells upon silencing of NOTCH3." (PMID 24143218, 2013). "Over-expression of CCND1 or amplification at the 11q13 region is also associated with poor prognosis and relapses in high-grade gliomas (normal brain tissues, low-grade gliomas, and high-grade gliomas were 4/18, 15/32, and 18/24), oligodendrogliomas, and ependymomas on supratentorial locations." (PMID 29416789, 2018). "A previous study identified FoxM1 as a downstream target of the canonical Wnt/β-catenin signaling pathway, wherein its nuclear accumulation, in conjunction with β-catenin, enhances the expression of c-Myc and Cyclin D1 in glioma cells." (PMID 41323781, 2025). "Parallel evaluation of cell proliferation through growth curve analysis and cyclin D1 expression, a well-known marker promoting glioma cell proliferation, revealed a similar dynamic." (PMID 41154863, 2025).
glioma (continued). "Our study confirmed that FoxM1 promotes c-Myc and Cyclin D1 expression and is localize in the nucleus as well as the cytoplasm in glioma cells." (PMID 41323781, 2025). "Our results demonstrated that the protein expression of Cyclin E1 and Cyclin D1 were obviously decreased, while the protein expression of P21 and P27 were significantly increased in glioma cells treated with NPS‐2143." (PMID 38509759, 2024). "Previous studies have demonstrated that CDK4 and cyclin D1 are both key modulators promoting the G1 transition in glioma cells." (PMID 37545464, 2024). "According to reports, HuR interacted with CircCCNB1 to increase the expression of cyclin D1 in glioma cells." (PMID 39614424, 2024). "We have analyzed the level of Reg-2 and its newly identified targets that encode the cyclins CCND1, CCNE1, CCNE2, CCNB1, CCNA2, and the kinases PLK1 and AURKA in glioma tumors." (PMID 38238463, 2024). "The expression of cell cycle‐related proteins was downregulated obviously after glioma cells being incubated with T+A@Glu‐NPs for 48h, including cyclin D1 and CDK4." (PMID 39544152, 2024). "Treatment with let-7f decreases proliferation while increasing G1 phase cell count and apoptosis of glioma cells by decreasing CCND1, CCNE1, and Bcl-2 expression, increasing P21, P27, and Bax expression, and increasing caspase-3 activity." (PMID 37370851, 2023). "As a result, the transcription of CCND1 is up-regulated, leading to an increase in the proliferation of glioma cells." (PMID 37861491, 2023). "Significantly decreased p397-FAK/FAK and increased cyclin D1 expression were also found in the LAIR1OE glioma tissues of mice." (PMID 37845206, 2023). "Altogether, these results demonstrated that c-Myc regulated by NAP1L1 promoted glioma cell proliferation by inducing CCND1/CDK4." (PMID 37770914, 2023). "Treatment with let-7b rescues cisplatin sensitivity of cisplatin-resistant glioma cells by binding to CCND1 mRNA 3′ UTR to decrease CCND1 expression, which increases caspase 3 activity, apoptosis, and G1 phase cell count." (PMID 37370851, 2023). "The potential therapeutic mechanism of miR‐29a/b/c in glioma is to inhibit tumor cell proliferation by downregulating cyclin D1 expression, phosphorylation of AKT, GSK‐3β, and thus inducing G1 blockade." (PMID 37786890, 2022). "Glioma-related oncogene homolog 1 (Gli1) was originally named in glioma research, which can affect glioma cell apoptosis and proliferation via regulated cyclin D1 and Bcl-2." (PMID 35874843, 2022). "In summary, we demonstrated that CDC42EP3 downregulation inhibited the malignant behaviors of glioma cells through regulating c-Myc-mediated transcription of CCND1." (PMID 35365622, 2022). "Rescue experiments were finally executed to verify the role played by CDC42EP3/CCND1 axis in human glioma U251 cells." (PMID 35365622, 2022). "The expression of cyclin D1 can act as a biological marker in evaluating the malignancy of gliomas and the prognosis of patients." (PMID 35223330, 2022). "All the results provide solid evidence that the regulation of glioma development by CDC42EP3 depends on CCND1 which is transcriptional activated by c-Myc." (PMID 35365622, 2022). "In EGFR mutated gliomas, the hyperactivation of EGFR leads to epigenetic changes, which promote cancer progression, such as the upregulation of c-Myc and cyclin D1 (CCND1)." (PMID 35681635, 2022). "Genes associated with the neuronal differentiation pathway (Pcsk9, Runx1, Cebpb, Fzd4, Wnt7a, Ascl1, Fzd2, Edn3, Olig2, and Gpc2), gliomas (Shc1, Cdk4, E2f2, and Ccnd1), and cell cycle (Bub1b, Bub, Ccnb1, Ccnb2, and Cdc20) were significantly downregulated." (PMID 36147849, 2022). "All of the results above indicated that knocking down CCND1 retarded pro-tumor effects mediated by upregulated CDC42EP3 in glioma." (PMID 35365622, 2022).
glioma (continued). "Downregulation of the PI3K/AKT pathway can restrain the expression of a variety of downstream molecules, such as Cyclin D1 and Bcl-2, thereby inhibiting the proliferation and enhancing the apoptosis of glioma cells." (PMID 36147923, 2022). "In this study, it was found that silvestrol considerably attenuated the proliferative potential of U251 and U87 glioma cells and reduced expression of cyclin D1." (PMID 35677890, 2022). "In a word, this study reported the tumor-promoting role of CDC42EP3 in glioma progression which probably functioned through targeting CCND1." (PMID 35365622, 2022). "This study confirmed the oncogenic roles of E2F1 and CCND1 and the anti‐tumorigenic role of miR‐107 in glioma." (PMID 34758200, 2021). "In cells, the RT‐qPCR and western blot assays suggested that the mRNA and protein expression of CCND1 were higher in glioma cell lines (U251, A172, T98G) than in Heb cells." (PMID 34758200, 2021). "Known prominent events include TMPRSS2-ERG in PCa, EGFR, CDK4, and MDM2 in glioma, and CCND1 in BrCa." (PMID 34891161, 2021). "More importantly, silencing HAS3 or treatment with the anti-CD44 antibodies decreased the levels of the cell cycle-related proteins cyclin B1 and cyclin D1 in glioma cells, and CQ treatment further enhanced this effect." (PMID 33986244, 2021). "Here, we found CCND1 was highly expressed in glioma tissues and cells, and its expression was reduced by miR‐107, but reduced by E2F1." (PMID 34758200, 2021). "Increasing studies show that many genes affect the viability and migration of glioma cells by regulating CCND1." (PMID 33676540, 2021). "This study suggested that E2F1 reduces miR‐107 transcription to induce CCND1 upregulation, which leads to progression of glioma via Wnt/β‐catenin signaling activation." (PMID 34758200, 2021). "The RT‐qPCR and immunochemistry (IHC) staining results indicated that the level of CCND1 was higher in glioma tissues than in normal tissues." (PMID 34758200, 2021). "Inhibition of cyclin D1 has resulted in enhanced sensitivity of glioma cells to temozolomide, pointing to its key role in the chemoresistance of GBM cells." (PMID 34070493, 2021). "Similar to our results, the reduction of miR-17 in glioma cells improves cell viability and migration ability by increasing the expression of CCND1, p-Akt and Akt." (PMID 33676540, 2021). "A study demonstrated that cyclin D1 is overexpressed in histologically high-grade gliomas (WHO), and that the higher expression level is positively correlated with poor prognosis." (PMID 34830034, 2021). "miR‐107 was poorly expressed, whereas E2F1 and CCND1 were highly expressed in glioma tissues and cells." (PMID 34758200, 2021). "CCND1 has recently been revealed to be highly expressed in glioma and reduced cancer cell apoptosis." (PMID 34758200, 2021). "It was reported that, in glioma cancer stem cells, c-Myc regulates cell cycle progression by controlling Cyclin D1 and p21WAF1/CIP1." (PMID 33330479, 2020). "Previous researchers have demonstrated that CCND1, identified as a proto-oncogene, has an essential role in the development of many kinds of tumours, including lung adenocarcinoma, glioma and renal cell cancer." (PMID 32660514, 2020). "In this way, to attain the potential molecular mechanisms by which CUL7 promotes glioma development, we detected the expression changes of some key mediators of cell proliferation and apoptosis, including p21, p27, cyclin D1, CDK4, cyclin E1 and CDK2." (PMID 32252802, 2020). "Clinically, the protein levels of Wnt1, β-catenin and cyclin D1 were positively correlated with the Karnofsky performance scale score and World Health Organization grades of patients with glioma." (PMID 31596734, 2019). "In this study, the expression of cyclin D1 in low-grade and high-grade gliomas was positive in 31.25% and 61.53% of samples, respectively." (PMID 31583003, 2019).
glioma (continued). "In line with CDKN2A loss-of-function and consecutive activation of the cyclin D1/cyclin dependent kinase (CDK) 4/6 complex, Rb was hyperphosphorylated in the majority of double-mutant glioma cells, indicating functional inhibition." (PMID 31391125, 2019). "Acting as a proto-oncogene, UCA1 was proved to promote the proliferation and cell cycle progression of glioma cells by upregulating cyclin D1 transcription." (PMID 31798345, 2019). "In glioma cells, inhibition of cyclin D1 blocked progression of the cell cycle, inhibited proliferation and induced apoptosis." (PMID 30498093, 2019). "We used cDNA microarray to screen the downstream gene of GATAD1 and found that CCND1 is the main target of GATAD1 in glioma cells." (PMID 31286678, 2019). "The results showed that the expression of cyclin D1 was associated with different tumor grades, especially the high level of expression in grade 4, and the amount of cyclin D1 increased as the level of grade glioma increased." (PMID 31583003, 2019). "The cell cycle regulator cyclin D1 was mathematically revealed and experimentally validated to control glioma differentiation, which is consistent with the discovery in this study." (PMID 31682596, 2019). "Our findings discover that SAE1 overexpression leads to increase of Akt SUMOylation and Akt phosphorylation (Ser473), which increases expression of CDK2, Cyclin D1, Bcl-2 and ultimately to promote glioma cell proliferation and progressin." (PMID 31345225, 2019). "Among the selected genes, 15 (Araf, Braf, Kras, Ccnd1, Cdk6, Igf1r, Nras, Pik3ca, Pik3r1, Pdgfra, Pdgfrb, Pdgfb, Akt1, Akt2, and Mdm2) were related to glioma and leukemia." (PMID 31523185, 2019). "In this study, we characterized that, by targeting CCND1, GATAD1 gene amplification is associated with GATAD1 overexpression and glioma progression." (PMID 31286678, 2019). "Functionally, we confirm GATAD1 as an epigenetic chromatin topological regulator that promotes glioma proliferation by targeting CCND1." (PMID 31286678, 2019). "After glioma C6 cells were transfected withmiR-17 mimics (50 nM) for 72 h, the protein expression of Cyclin D1 (p < 0.001), p-AKT (p < 0.001) and AKT (p < 0.05) decreased compared to Lipofectamine and negative control groups." (PMID 29351283, 2018). "In conclusion, we demonstrated for the first time that the low miR-17 levels in glioma cells increased cell viability and migration, which correlates with increased expression of Cyclin D1, p-Akt and Akt." (PMID 29351283, 2018). "The expression of miR-17 was significantly lower (p < 0.01), and the protein expression of Cyclin D1 was markedly higher in rat glioma C6 cells compared to normal brain tissue (p < 0.001)." (PMID 29351283, 2018). "Protein expression of Cyclin D1 in rat glioma C6 cells and normal brain tissue was measured by Western Blot." (PMID 29351283, 2018). "The reduced miR-17 levels in glioma cells increased cell viability and migration, which correlates with increased expression of Cyclin D1, p-Akt and Akt." (PMID 29351283, 2018). "The protein expression of Cyclin D1, p-Akt and Akt in glioma C6 cells decreased after transfection with miR-17 mimics for 72 h, and increased after transfection with miR-17 inhibitor for 72 h." (PMID 29351283, 2018). "NF-κB regulates the transcription of cyclin D1 (an important factor for G1 progression and G1/S transition) and Bcl-2 (anti-apoptotic gene) in glioma cells." (PMID 29410396, 2018). "After glioma C6 cells were transfected with inhibitor of miR-17 (200 nM) for 72 h, the protein expression of Cyclin D1 (p < 0.05), p-AKT (p < 0.001) and AKT (p < 0.01) increased compared to Lipofectamine and negative control groups." (PMID 29351283, 2018). "This would be similar to the effect of sFRP4 in glioma and head and neck cancers, where we demonstrated that it downregulates the proproliferation genes cyclin D1 and c-myc." (PMID 28807014, 2017).
glioma (continued). "In this study based on Chinese Han population, we found a significant association between rs603965 within CCND1 gene, rs1346787 and rs3791679 within EFEMP1 gene and increased glioma risk, after covariates adjustment." (PMID 28380465, 2017). "Of great interest, SOX7 was reported to downregulate Wnt/β-catenin transcription and decrease the expression of Cyclin D1 and c-Myc in glioma." (PMID 29029454, 2017). "In agreement with previous studies, the results showed that the expression levels of nuclear β-catenin, as well as its downstream targets Cyclin D1 and c-Myc, were markedly increased in glioma tissues and cell lines." (PMID 29029454, 2017). "Logistic analysis showed the significant association of rs603965 within CCND1 gene, rs1346787 and rs3791679 in EFEMP1 gene with increased glioma risk, after adjustment for gender, age, smoking and alcohol drinking." (PMID 28380465, 2017). "Glioma risks were higher in carriers of homozygous mutant of rs603965 within CCND1 gene, rs1346787 and rs3791679 in EFEMP1 gene than those with wild-type homozygotes, OR (95%CI) were 1.67 (1.23-2.02), 1.59 (1.25-2.01) and 1.42 (1.15-1.82), respectively." (PMID 28380465, 2017). "The results showed that the level of nuclear β-catenin and its target gene (Cyclin D1 and c-Myc) expression was markedly increased in glioma tissues and cell lines compared with normal tissues or NHA, respectively." (PMID 29029454, 2017). "Polymorphism in rs603965 within CCND1 gene and rs1346787 within EFEMP1 gene and its gene- gene interaction were associated with increased glioma risk." (PMID 28380465, 2017). "In conclusion, we found a significant we found a significant association between rs603965 within CCND1 gene, rs1346787 and rs3791679 within EFEMP1 gene and increased glioma risk." (PMID 28380465, 2017). "So in this study, we aimed to the impact of CCND1 and EFEMP1 gene polymorphism, and additional their gene-gene interactions and haplotype within EFEMP1 gene on glioma risk based on Chinese population." (PMID 28380465, 2017). "So in this study, we investigated the impact of interaction between CCND1 and EFEMP1 gene polymorphism on glioma risk." (PMID 28380465, 2017). "The binding acetyl-histone 3 and 4 to p21, p27, Cyclin D1, c-myc and Nanog promoters were increased after glioma cells were treated with SAHA." (PMID 27911270, 2017). "We showed that the increase in noise due to the ultrasensitive response of cyclin D1 in response to drug treatment can induce bifurcation and heterogeneous responses in glioma differentiation." (PMID 27515956, 2016). "Comparison of these two situations demonstrated that inhibition of cyclin D1 feedback enhances the differentiation potential of CT-treated glioma cells." (PMID 27515956, 2016). "This implies that increasing noise strength in signal transduction can induce bifurcation of cyclin D1 degradation, which renders some glioma cells insensitive to drug treatment and induces heterogeneous activation of GFAP." (PMID 27515956, 2016). "These sensitive parameters indicate the critical role of cyclin D1 in regulating glioma differentiation." (PMID 27515956, 2016). "First, the expression of AEG-1 and its downstream cyclin D1 are increased in both U251 and U87 malignant glioma cells by treatment with TGF-β1 (5 ng/ml) for 1, 3, 6, 12 and 24 hours." (PMID 26909607, 2016). "To further demonstrate the regulatory role of cyclin D1 in the glia-fate induction of glioma cells, we introduced a functional pharmacologic inhibitor of CDK4 and 6 which bind to cyclin D1 to form a complex required for G1-S cell cycle phase progression." (PMID 27515956, 2016).